ANXA1 (annexin A1)
Diseases named in the same sentence as ANXA1 in open-access papers (continued):
Sharing a sentence is not in itself a finding about the gene and the disease.
Stroke (continued). "An intriguing aspect of the BBB in neurovascular diseases such as stroke lies in the interactions of estrogen and ANXA1, and the possible role this protein plays in the vasculo-protective action of the hormone." (PMID 27655189, 2016). "Blocking ANXA1 with an antagonist (Boc1) or genetic deletion of ANXA1 eliminated the protective effects of CH against stroke damage, further confirming the role of ANXA1 in CH-mediated neuroprotection against stroke." (PMID 38639785, 2024). "Notably, ANXA1’s influence on microglial function alteration, its anti-inflammatory properties, and its connection to stroke-induced inflammatory pathways are highlighted." (PMID 38639785, 2024). "The group also suggested the role of ANXA1 as an anti‐inflammatory mediator in cardiovascular therapeutics should not be overlooked and have highlighted several studies that show the benefits of ANXA1 and its synthetic peptide in atherosclerosis, stroke and MI." (PMID 35146757, 2022). "Chronically high levels of cortisol may lead to unresolved inflammation, which can be monitored with annexin-A1, resulting in conditions such as diabetes, stroke, and obesity." (PMID 34574438, 2021). "ANXA1 has also protective role in myocardial infarction (MI) and stroke." (PMID 33804219, 2021). "For instance, in several murine stroke models, AnxA1 administration mediated protective effects via FPR2 after cerebral ischemia/reperfusion (I/R) injury or more recently, after spontaneous intracerebral hemorrhage, limiting further cerebral microvascular dysfunction and tissue damage." (PMID 33810523, 2021). "As such, we treated mice with AnxA1 before stroke and then performed light/dye thrombosis." (PMID 31154815, 2019). "Plasma levels of AnxA1 were found to be lower in stroke patients versus the control group." (PMID 31154815, 2019). "Given the impact of subsequent thrombotic events in stroke, we finally assessed whether AnxA1 had a similar impact on thrombus formation in mice after cerebral I/RI." (PMID 31154815, 2019). "ANXA1 may also confer a therapeutic potential in protecting against stroke, as seen using a murine-model of stroke induced by mid-cerebral artery occlusion." (PMID 29614751, 2018). "Upregulation of Anxa1 in vivo, improves atherosclerosis (decreased lesion size, inflammation, improved plaque stability), myocardial infarction (decreased infarct size, inflammation and increased survival) and stroke (decreased infarct size, inflammation)." (PMID 30213070, 2018). "A growing body of evidence also points at an anti-inflammatory and neuroprotective function of AnxA1 in the brain, and AnxA1-derived molecules might emerge as promising tools in the treatment of brain diseases, including stroke and neurodegenerative disorders." (PMID 29914106, 2018). "Most notably, administration of human recombinant ANXA1 has been shown to markedly reduce lesion size, clinical score and markers of leukocyte infiltration in murine mid-cerebral artery occlusion models of stroke." (PMID 27655189, 2016). "While it is not known if the low ANXA1 persists before stroke and can be linked to underlying conditions for stroke such as atherosclerosis, this finding suggest that plasma ANXA1 may predict clinical outcomes of AIS and the effectiveness of EVT therapies." (PMID 34022892, 2021). "Finally, we report a previously unknown role for AnxA1 as a preventative strategy both for cerebral I/RI (by its ability to reduce cerebral thrombosis, a prerequisite for stroke) and for subsequent thrombotic events after I/RI." (PMID 31154815, 2019). "AnxA1–/– mice have a heightened inflammatory response as displayed by increased leukocyte transmigration, higher levels of inflammatory markers in a model of localized joint inflammation, increased neurological deficit in a stroke model and delayed repair in a model of colitis." (PMID 23230437, 2012).
Stroke (continued). "In addition, consistent with these observations, absence of AnxA1 also leads to increased inflammation and in some cases a higher mortality in life-threatening inflammation-associated conditions, e.g., stroke." (PMID 23230437, 2012). "Moreover, when ANXA1 was administered to mice before and after cerebral ischemia-reperfusion injury, the blood flow was significantly improved, indicating ANXA1-mediated an inhibitory effect on thrombosis as well as displayed its protective effects against recurrent post-stroke thrombotic events." (PMID 36834844, 2023). "Previous research from our laboratory has shown that when aspirin is administered to mice with experimental stroke, they can produce ATL, which triggers pro-resolving responses through the engagement of the AnxA1/Fpr2/ALX pathway." (PMID 33202930, 2020). "Furthermore, we provide novel evidence that AnxA1 is not only able to reduce the effects of cerebral I/RI (including reducing the effect of subsequent thrombi forming after cerebral ischemia), but it is able to reduce cerebral thrombosis, a prerequisite for stroke." (PMID 31154815, 2019). "At day 7 after stroke, 79% of cells expressing the polymorphonuclear cells (PMN) antigen also expressed ANXA1." (PMID 29286319, 2017). "The negative outcome after stroke is increased with aging, and the lack of the increase of ANXA1 expression in classical monocytes might be a confounding factor." (PMID 39475881, 2024). "By disrupting the SIRT5–ANXA1 interaction and facilitating SIRT5 clearance, this strategy enhances ANXA1 membrane localization and secretion, ultimately reducing infarct volume, preserving neuronal integrity, and improving neurological outcomes in stroke models—all without apparent toxicity." (PMID 41007413, 2025).
Sepsis (26 papers, 2012 to 2025). Sepsis is defined as life-threatening organ dysfunction caused by a dysregulated host response to infection. "This study investigated the protective role of Annexin A1 (ANXA1) in sepsis‐associated encephalopathy (SAE) by examining its effects on brain vascular endothelium and blood–brain barrier (BBB) integrity." (PMID 39727329, 2024). "The concentration of MT-ND6 and ANXA1 were significantly elevated in the patients with sepsis, and the diagnostic values of MT-ND6 (0.789) for sepsis patients was second only to SOFA scores (AUC = 0.870)." (PMID 39611143, 2024). "And the results showed that higher serum MT-ND6 levels (≥ 1.41 ng/mL) as well as lower serum ANXA1 levels (< 8.09 ng/mL) were respectively associated with higher probability of 30-day mortality in patients with sepsis." (PMID 39611143, 2024). "In the present study, we try to explore the diagnostic and prognostic values of MT-ND6 and ANXA1 in patients with sepsis, and to explore the potential role of these two molecules in people with different immune states, aiming at providing assistance for subsequent immunomodulatory." (PMID 39611143, 2024). "This study aimed to verify the hypothesis that ANXA1 (Ac2-26) inhibits inflammation and apoptosis through the Fpr2 receptor to alleviate sepsis-induced AKI and explore its underlying mechanism." (PMID 36544058, 2023). "The observation that reduced ANXA1 levels are associated with increased severity of septic conditions suggests that ANXA1 could be a potential biomarker for the progression and severity of sepsis‐related neurological complications." (PMID 39727329, 2024). "In sepsis and septic shock, ANXA1 and its derivative peptides show great potential in reducing inflammation and improving prognosis." (PMID 41208642, 2025). "Collectively, ANXA1 and its derived peptide can be protective against sepsis and sepsis‐induced organ damage by improving mitochondrial biosynthesis and inhibiting oxidative stress, apoptosis, autophagy, and ferroptosis." (PMID 41208642, 2025). "There are various indications that ANXA1 is closely related to the occurrence and development of sepsis." (PMID 41208642, 2025). "Similar to the findings above, the sepsis patients had significantly higher levels of MT-ND6 and ANXA1 compared with ICU non-sepsis patients in the validation cohort." (PMID 39611143, 2024). "Our research showed that MT-ND6 and ANXA1 were more effective in the short-term prognosis of sepsis than commonly used laboratory markers like PCT, CRP, IL-6 and HBP." (PMID 39611143, 2024). "ANXA1 is an independent protector for sepsis, whose decreasing was related to the elevated mortality in severe septic patients." (PMID 39611143, 2024). "Targeting anti-inflammatory ANXA1 and its receptors have achieved satisfyingly protective effects in many inflammation diseases, including sepsis-induced acute kidney injury (SI-AKI) and endotoxin-induced cerebral inflammation." (PMID 39611143, 2024). "We measured serum MT-ND6 or ANXA1 in a cohort of patients with sepsis in ICU (n=180) and patients with non-sepsis in ICU (n=60) by Enzyme-linked immunosorbent assays (ELISA)." (PMID 39611143, 2024). "ANXA1 knockout in mouse models lead to chronic inflammation, including lung fibrosis, sepsis, rheumatoid arthritis and atherosclerotic lesion formation." (PMID 38443832, 2024). "In this study, we detected the plasma levels of MT-ND6 and ANXA1 on ICU admission for diagnosing sepsis patients and predicting their 30-day mortality." (PMID 39611143, 2024). "Second, there is a need to explore the therapeutic potential of ANXA1‐derived peptides as interventions for sepsis‐induced cognitive impairment." (PMID 39727329, 2024). "On the day of ICU admission, the serum MT-ND6 and ANXA1 levels of septic patients was significantly elevated than the ICU non-sepsis patients and healthy controls." (PMID 39611143, 2024).
Sepsis (continued). "Our findings provide valuable models testing patient risk prediction and strengthen the evidence for agonists of FPR1, MT-ND6 and ANXA1, as novel biomarker for patient selection for novel therapeutic agents to target mtDAMPs and regulator of GPCRs in sepsis." (PMID 39611143, 2024). "Higher serum concentrations of MT-ND6 (>1.41 ng/ml) and lower concentrations of ANXA1 (< 8.09 ng/mL) were closely related to the higher mortality in patients with sepsis, with the predictive values were 0.705 and 0.694, respectively." (PMID 39611143, 2024). "To further study the effects of ANXA1 on the levels of inflammatory cytokines at the cellular level during sepsis, we constructed an experimental cell model by inducing HK-2 cells with LPS (10 μg/ml) for 24 h." (PMID 36544058, 2023). "First, we found that the level of endogenous ANXA1 in the kidney tissue in the sepsis group was significantly lower than that in the controls." (PMID 36544058, 2023). "Related studies have shown that ANXA1 (Ac2-26) protects against myocardial injury in rats with sepsis by negatively regulating myocardial apoptosis." (PMID 36544058, 2023). "In contrast, plasma ANXA1 was shown to be decreased in sepsis patients compared to healthy controls." (PMID 35146757, 2022). "The AnxA1-Fpr2 system also has a crucial function in hindering the resolution of cerebral inflammation in lipopolysaccharide (LPS)-induced sepsis." (PMID 33318141, 2021). "Annexin A1 mRNA levels were increased during all phases of sepsis-induced critical illness (all p < 0.05 versus healthy control mice)." (PMID 33593393, 2021). "Among the sustained upregulated genes in neutrophils post sepsis, we identified ANXA1, MMP9, SIPR1, and JUN as the candidate genes." (PMID 33761636, 2021). "The deregulation of DEGs including AKT1 (down), IFN-inducible protein 6 (IFI6, down), IL-15 (up), and ANXA1 (up) was verified in the neutrophils from patients with sepsis-induced immunosuppression as compared with controls." (PMID 33761636, 2021). "Many researches and our previous studies have found that the ANXA1 plasma levels were decreased in the rabbit and patients with severe sepsis." (PMID 27833268, 2016). "There was evidence that endogenous Anxa1 exhibited a protective role in the cerebral microcirculation of sepsis." (PMID 25242054, 2014). "In the present study, we investigated the suppressive effect of XBJ on the development of A. baumannii-induced sepsis in rats by not only increasing the expression of annexin A1 but also decreasing the serum release of either IL-8 or TNF-α." (PMID 24369483, 2013). "For lungs harvested from sepsis-control groups, annexin A1 concentration was elevated and the positive spots distributed unevenly in lung tissue as the inoculation time prolonged from 6 hrs to 24 hrs." (PMID 24369483, 2013). "In particular, alveolar epithelial cells of the lungs in the sepsis + XBJ groups showed more intensely positive reaction for annexin A1 than those of the sepsis-control groups at the same time points." (PMID 24369483, 2013). "Treatment of XBJ added a positive effect on the elevation of annexin A1 expression when simultaneously administrated with A. baumannii (P < 0.05), and the enhancement amplitude was most pronounced in sepsis + XBJ group at 24 hrs after injection." (PMID 24369483, 2013). "Overall, data showed that in rats with A. baumannii infection, annexin A1 was upregulated in a time-dependent fashion during the course of sepsis and XBJ added a positive effect on this anti-inflammatory enhancement activity by an early administration." (PMID 24369483, 2013). "Annexin A1 protein level was significantly increased in sepsis-control group as compared with normal-control group for the same time period (P < 0.05)." (PMID 24369483, 2013). "Furthermore, derived peptides with similar biological effects to ANXA1 have also been studied in sepsis." (PMID 41208642, 2025).
Sepsis (continued). "Therefore, a series of experimental studies was conducted to clarify the potential role of ANXA1, a potent anti‐inflammatory molecule, in the diagnosis and treatment of sepsis and septic shock." (PMID 41208642, 2025). "Circulating AnxA1 levels were increased in a subgroup of patients with sepsis." (PMID 39262873, 2024). "Furthermore, the finding that ANXA1 deficiency exacerbates inflammation, endothelial dysfunction, and BBB disruption highlights the importance of ANXA1 in the pathophysiology of sepsis‐induced brain injury." (PMID 39727329, 2024). "As an anti-inflammatory molecule, ANXA1 was involved in the sepsis process." (PMID 39624089, 2024). "Notably, the survival rates of Anxa1−/− mice were notably lower than those of wild type mice, underscoring the protective role of Anxa1 in the context of LPS-induced sepsis." (PMID 38961424, 2024). "The results were in line with our expectations, that low levels of ANXA1 (< 8.09 ng/mL) was able to predict the 30-day mortality, and the binary logistic regression analysis verified that ANXA1 was an independent protective factor in sepsis (B = -0.098, OR = 0.835, P = 0.020)." (PMID 39611143, 2024). "However, it was reported that the Anxa1 plasma level decreased in patients with sepsis, as compared with control patients." (PMID 25242054, 2014). "It indicated that Anxa1 had a key role in sepsis progression and that the expression of Anxa1 may be different in the lymph and plasma of patients." (PMID 25242054, 2014). "However, our results differed from previous studies in which it had been shown that annexin A1 decreased in sepsis patients or obese patients with chronic inflammatory phenotype." (PMID 24369483, 2013). "Nevertheless, the response of annexin A1 in the process of A. baumannii infection and whether this novel mediator is able to be used as a new biomarker in the diagnosis of sepsis remain to be elucidated." (PMID 24369483, 2013). "Here, an interesting and noticeable finding must be rendered is the ability of XBJ to increase annexin A1 expression at each monitored time point determined by both western blotting and immunohistochemical analysis, when compared with that of sepsis-control group." (PMID 24369483, 2013). "First, upcoming investigations should aim to elucidate the precise regulatory mechanisms underlying the interaction between ANXA1 and the VEGF‐A/VEGF‐R2 signaling pathways in brain endothelial cells, particularly focusing on their impact on blood–brain barrier (BBB) integrity during sepsis." (PMID 39727329, 2024). "Thus, we proposed that CRISP3 may contribute to the development of sepsis by affecting the expression or function of ANXA1 or A1BG." (PMID 39624089, 2024). "The results presented indicate that ANXA1 plays a crucial role in maintaining BBB integrity and protecting against sepsis‐induced brain dysfunction." (PMID 39727329, 2024). "Second, there are many ligands of FPR1, including the HSP, lipoxin A4, cathepsin G and so on, we only detected the concentration of MT-ND6 and ANXA1 in this study, which was insufficient to revel the comprehensive functions of FPR1 in sepsis." (PMID 39611143, 2024). "The study concludes that ANXA1 reduces BBB permeability to protect against sepsis‐induced brain dysfunction via VEGF‐A/VEGF‐R2 regulation of tight junction proteins, suggesting ANXA1 as a potential therapeutic for SAE." (PMID 39727329, 2024). "Lastly, transitioning toward clinical research, it will be pivotal to assess ANXA1's viability as a biomarker for neuroinflammation and BBB integrity in patients with sepsis." (PMID 39727329, 2024). "Our present study showed the reverse expression profiling between the ANXA1 (up) and AKT1 (down) in the neutrophil samples from patients with sepsis-induced immunosuppression." (PMID 33761636, 2021).